ALK (ALK receptor tyrosine kinase)
Diseases named in the same sentence as ALK in open-access papers (continued):
Sharing a sentence is not in itself a finding about the gene and the disease.
tumor (continued). "According to gene mutation types, tumor driver gene-derived inhibitors (including EGFR inhibitor, ROS1 inhibitor, and ALK inhibitor) have been screened and used for stratifying treatments in NSCLC patients." (PMID 31572680, 2019). "In preclinical studies, mice treated with an oral dose of TSR-011 60 mg/kg showed complete ALK inhibition in Karpas-299 tumours at 8 h, with a plasma concentration of 698.00 nmol/L." (PMID 31217479, 2019). "Tumor samples from five patients were subjected to RNA capture sequencing to identify ALK gene fusion partners." (PMID 32914017, 2019). "Patients with epidermal growth factor receptor (EGFR) or activating anaplastic lymphoma kinase (ALK) genomic tumor aberrations should have disease progression on NMPA-approved therapy." (PMID 31221221, 2019). "Tumour tissue currently uses a threshold of 15% of ALK-rearranged cells for the diagnosis of an ALK-rearrangement positive tumour." (PMID 30889898, 2019). "Briefly, NanoVelcro platform showed improved CTC-capture efficiency than CellSearch system, and the ALK-rearrangement status of captured CTCs kept in accordance with results from tumor specimen." (PMID 30658713, 2019). "In the tumours with partial 2p gain, the extra chromosomal segments varied in size from 25 to 130 Mb and included both ALK and MYCN except in 6 patients (data available on request)." (PMID 30778092, 2019). "Fluorescence in situ hybridization (FISH) analysis using ALK break-apart probes produced a positive result, as indicated by the presence of isolated green (5’ALK) and orange (3’ALK) signals in the tumor cell nuclei, flanking the ALK locus at 2p23." (PMID 29747676, 2018). "Instead, elevated levels of stem-cell factor (SCF), the ligand for KIT, in the surrounding tumor stroma appears to be required to bypass inhibition of ALK signaling." (PMID 29455675, 2018). "The combined inhibition of BRAF and ALK stopped tumour growth, supporting the clinical relevance of our findings." (PMID 30290811, 2018). "A tumor biopsy sample collected from the patient was ALK fusion-positive and crizotinib was subsequently applied, which stabilized the patient’s disease for 18 months." (PMID 29764505, 2018). "The use of selective inhibitors such as anti-EGFR or anti-ALK therapies in patients can lead to tumor shrinkage and prolonged survival." (PMID 29890761, 2018). "The ALK vaccine in combination with ALK TKI treatment significantly delayed tumor relapse after TKI suspension." (PMID 29495603, 2018). "Tumor flare reaction has also been described in some case reports of patients with ALK rearranged tumors that discontinued ALK TKI." (PMID 30250648, 2018). "To further confirm the specific mechanism by which MIR503HG regulates ALK-positive cell proliferation, we analyzed tumor specimens from nude mice injected with MIR503HG-overexpressing SR-786 or KARPAS cells." (PMID 29758012, 2018). "Particularly, the current methods for detecting ALK fusion genes require tumor tissue specimens, such as surgically resected or biopsied tumor tissue, or malignant pleural effusion fluid." (PMID 29587818, 2018). "Almost 30 years after the identification of the NPM-ALK fusion, similar ALK tyrosine kinase fusions have been found in other tumor types." (PMID 29455648, 2018). "Reflecting the high frequency of ALK F1174L in primary NB, several combinatorial approaches have been taken to overcome crizotinib resistance or enhance its anti-tumour activity in cell lines and xenografts driven by this ALK mutant." (PMID 29642598, 2018). "Secondly, the computerized analyses of the tumor specific ALK signal obtained with the MTP-IF correlated with the H-score values attributed to the IHC stainings." (PMID 30326973, 2018).
tumor (continued). "Further innovation with third-generation ALK inhibitors and next-generation tumor sequencing will allow practitioners to further tailor treatment to patients’ individual tumor genetics." (PMID 30564472, 2018). "The transcript fusion of EML4 exon 18 to ALK exon 20 was identified in both the patient’s tumor and crizotinib-6 xenografts." (PMID 29764505, 2018). "All of these 3 tumors were confirmed to be ALK-positive by IHC (i.e. > 50% of the tumor), and the ALK-positive areas were largely restricted to the undifferentiated areas." (PMID 29535836, 2018). "Four ALK positive patients with progressive disease following crizotinib treatment were identified with paired pre- and post-crizotinib tumor tissue from our previously published cohort." (PMID 29300322, 2018). "Molecular alterations including KRAS mutations, EGFR mutations, and ALK/ROS1 re-arrangements were detected in 23.2%, 19.6%, and 5.4% of analyzed tumor samples, respectively." (PMID 29707129, 2018). "Studies based on resistant and sensitive cell lines and those based solely on post-resistant tumor tissues have suggested that the epithelial-mesenchymal transition (EMT) potentially mediates resistance against ALK inhibitors." (PMID 29300322, 2018). "Promising data on beneficial effects of combined ALK-inhibition and carbon ion irradiation reported in this study suggest further validation of this concept in preclinical in-vivo tumor models." (PMID 29304828, 2018). "Our study demonstrated that c-Met overexpression of ≥50% of tumor cells of strong staining exists in a small population of advanced ALK-rearranged NSCLC." (PMID 30477470, 2018). "Peptide-specific CD4 T cell lines raised from one patient recognized and lysed ALK-positive tumor cell lines in an MHC class II restricted manner." (PMID 29642597, 2018). "This is observed in complex case #5 where the patient was able to achieve prolonged survival on three different ALK inhibitors by switching between ALK inhibitors and cytotoxic chemotherapy to circumvent progression and tumor resistance." (PMID 30042820, 2018). "Simultaneous treatment of the mTOR/ALK-positive graft with rapamycin and crizotinib was more effective than rapamycin as mono-drug: tumor shrinkage in four and growth stagnation in one of five MPM tumors was achieved." (PMID 29755689, 2018). "The ALK/MET inhibitor crizotinib enhanced the anti-tumor effect of the mTOR-inhibitor rapamycin in a patient-derived MPM xenograft with co-activated ALK/mTOR: combined therapy achieved tumor shrinkage in 4/5 tumors and growth stagnation in one tumor." (PMID 29755689, 2018). "For the prescription of such regimens, the reliable assessment of ALK protein expression and its alteration on sequential tumor biopsies together with corresponding genomic data is of high importance." (PMID 30326973, 2018). "As shown on the images and the plot, a strong signal intensity for ALK protein in the cytosol of tumor epithelia was reached already after 4 min of primary antibody incubation." (PMID 30326973, 2018). "Thirteen out of the 14 tumors that expressed ALK-I19 also showed strong ALK expression, as defined by > 50% of tumor containing areas showing strong ALK immunostaining, a criterion used in a previous publication." (PMID 29535836, 2018). "mTORC1 inhibition by rapamycin sensitized the tumor to crizotinib: Simultaneous treatment inhibited the activity of ALK and consequently its targets STAT3 and AKT, while crizotinib as single agent did not." (PMID 29755689, 2018). "One of the limitations of FISH for ALK on cytological samples is the number of tumor cells, which is sometimes less than 100 thereby making difficult the analysis as a function of the required cut off." (PMID 29534030, 2018). "Ganetespib, an inhibitor of HSP90, has been tested on NSCLC independently and in combination with crizotinib and other ALK inhibitors, showing improved anti-tumor effects both in vitro and in vivo, as compared to ALK inhibition alone." (PMID 29455675, 2018).
tumor (continued). "We confirmed by FISH that the tumor harbored an ALK rearrangement, but the ALK-IHC score was zero during chemotherapy, and crizotinib was administered as second-line chemotherapy; after 8 weeks, the disease had progressed." (PMID 29844868, 2018). "ALK translocation and HER2/3 mutations are capable to induce their pro tumor proliferative effect through MEK, a downstream effector of MAPK pathway." (PMID 29455653, 2018). "Vascular endothelial growth factor-A (VEGF-A) production and tumor vessel formation were found to be more significantly enriched in ALK-rearrangement NSCLC than that in epidermal growth factor receptor or Kirsten rat sarcoma viral oncogene mutated NSCLC." (PMID 29318404, 2018). "ALK is an ideal tumour antigen for targeted inhibition, given its restricted distribution in normal tissue and frequent expression in NB." (PMID 29642598, 2018). "Tumor cells with an ALK fusion are highly sensitive to tyrosine kinase inhibitors (TKIs) that target ALK, which include crizotinib and the second-generation ALK inhibitors, ceritinib, brigatinib, and alectinib." (PMID 29300322, 2018). "Subsequently, ceritinib demonstrated higher anti-tumor efficacy in ALK-rearranged NSCLC patients previously treated with chemotherapy and crizotinib as well as in crizotinib naïve patients during ASCEND-2 and ASCEND-3 clinical trials." (PMID 29495603, 2018). "To date, ALK has been considered to be an attractive therapeutic target in tumours that contain an activated ALK." (PMID 29760954, 2018). "We also used the 5′ and 3′ expression imbalance strategy to detect ALK fusion genes in the plasma of ALK fusion gene (+) samples that were confirmed by NGS of tumor tissues." (PMID 29587818, 2018). "In chromosomal translocation, ALK fusion proteins lead to ligand-independent constitutive activation of key pathways for oncogenesis and tumor progression." (PMID 29747676, 2018). "In all 12 surgical specimens, the ALK specific signal was detected on tumor epithelia above the stromal background intensity." (PMID 30326973, 2018). "ALK fusion proteins are constitutively active tyrosine kinases with an essential role in lymphomagenesis and tumor survival." (PMID 29642597, 2018). "Alternative pathway activation involving EGFR, KRAS, KIT, ERBB, MET and IGF-1R are also responsible for ALK+ tumor crizotinib resistance." (PMID 29455659, 2018). "Despite exceptional initial tumor responses to ALK inhibition by crizotinib, durable clinical response is limited and the emergence of drug resistance occurs." (PMID 29507657, 2018). "Based on the present clinical evidence it is difficult to say under which circumstances/factors, amplification of ALK gene is sufficient enough to render the tumor cells resistant." (PMID 29495603, 2018). "EMT has been reported to confer resistance against first and second generation ALK TKIs in NSCLC cell lines as well tumor samples." (PMID 29495603, 2018). "The second ones are the FDA approved anaplastic lymphoma kinase (ALK) inhibitors (e.g., crizotinib and ceritinib), which show positive effects in tumours harbouring ALK gene rearrangements." (PMID 30104481, 2018). "This is further demonstrated by the homogenous staining for the ALK protein in all tumor cells of the IHC-positive/FISH-BL-positive cases and further underlines that the occurrence of discrepant ALK results for IHC and FISH is due to technical reasons of FISH." (PMID 30466405, 2018). "The characteristics of the humoral and cellular immune response against ALK as well as tumor immune escape mechanisms have been increasingly investigated." (PMID 29642597, 2018).
tumor (continued). "It has been shown that ALK-positive patients have higher levels of vascular endothelial growth factor-A (VEGF-A) and tumor vessel formations compared to EGFR and KRAS mutated NSCLC." (PMID 29318404, 2018). "Generally, only a minority of tumour cells was ALK-positive and those positive cells tended to be scattered randomly throughout the tumour as isolated cells or small clusters." (PMID 30290811, 2018). "Inhibition of ALK activation prevents downstream signaling of cell proliferation and decreases tumor survivability." (PMID 30564472, 2018). "It is the first study showing the clinical improvement of crizotinib for ALK-rearranged patients with c-Met overexpression of ≥50% of tumor cells of strong immunostaining." (PMID 30477470, 2018). "In another study, lorlatinib was found to significantly reduce growth of tumours in the ALK F1174L/MYCN-driven genetically engineered mouse model of aggressive NB, which did not respond to crizotinib." (PMID 29642598, 2018). "Several ALK-independent resistance mechanisms have been proposed based on studies in post-crizotinib tumor samples and cell line models." (PMID 29300322, 2018). "In our experience, the staining intensity, in addition to the percentage of tumor cells showing ALK immunostaining, is important." (PMID 29535836, 2018). "Our group recently performed analysis of circulating tumor DNA from ALK+ patients collected prior to initiating treatment and at time of progression on ALK inhibitor." (PMID 29507657, 2018). "Tumor cells in ALK-positive ALCL cells are often surrounded by abundant reactive bystander cells which suggest an accompanying immune reaction." (PMID 29642597, 2018). "As with any targeted therapy, ALK-driven NSCLC tumor cells inevitably acquire drug resistance, leading to clinical relapse." (PMID 29495603, 2018). "Crizotinib has demonstrated concentration-dependent inhibition of ALK and c-Met phosphorylation in cell-based assays of tumour cell lines and has also demonstrated antitumor activity in mice with tumour xenografts that express ALK fusion proteins or c-Met." (PMID 29298713, 2018). "The 5′/3′ imbalance strategy for quantitative reverse transcription-PCR (RT-qPCR) was developed to detect ALK fusion genes in circulating tumor RNA (ctRNA) of NSCLC patients." (PMID 29587818, 2018). "The use of immunohistochemical markers such as CD30, epithelial membrane antigen (EMA), and ALK has increased the detection rate to 40%, highlighting the hidden tumor cells." (PMID 29617304, 2018). "A direct molecular link between ALK activation and suppression of the anti-tumor immune response has been shown by the Wasik group." (PMID 29642597, 2018). "Here, we examined ALK, MET and mTOR as potential therapeutic targets and determined the combinatorial efficacy of ALK and mTOR targeting on tumor cell growth in vivo." (PMID 29755689, 2018). "Given the restricted physiologic expression of ALK in only a few neuronal tissues, the inhibition of ALK for cancer therapy should theoretically have high specificity for tumor cells and result in few systemic toxicities." (PMID 28895885, 2017). "ALK copy numbers assessed using ddPCR of tumor gDNA from patients 2, 3, 5 and 6 were in complete accordance with the diploid ALK status determined by FISH or qPCR." (PMID 29156716, 2017). "Surprisingly, all patients with ALK gene rearrangement demonstrated PD-L1 expression on tumor cells." (PMID 28969070, 2017). "Dysregulation of miRNA expression and regulation has been shown to affect several signaling pathways in ALK carcinogenesis and control tumor growth, both in cell lines and mouse models." (PMID 28771164, 2017). "It is noteworthy that some studies reported ALK translocation in non-tumor tissue, but below the accepted thresholds for determined the ALK status positivity." (PMID 28805682, 2017). "Considering the tumor was spreading all over the abdominal cavity and that ALK staining of the tumor was positive, crizotinib was suggested as adjuvant therapy." (PMID 28535796, 2017).
tumor (continued). "First, ALK expression was significantly higher in tumor cells in hypervascular lesions as compared to those adjacent to necrotic foci in GBMs, and was positively correlated to the microvascular density as determined by CD34 expression." (PMID 28837676, 2017). "Detection of ALK/ROS1 rearrangements is currently based on IHC or fluorescence in situ hybridization (FISH) in NSCLC tumor samples." (PMID 29312651, 2017). "Fluorescence in situ hybridization was performed to study ALK rearrangements and immunohistochemistry to study ALK expression in tumor tissue." (PMID 28359267, 2017). "Some tumor-linked genetic alterations, such as in EGFR, BRAF, ALK, KIT, PDGFR, HER2, and KRAS, were only detected via ctDNA-based assays." (PMID 28392479, 2017). "In GBM tissues, strong ALK (5A4) immunoreactivity was frequently observed in perivascular tumor cells, in contrast to the relatively weak expression in those of perinecrotic areas, a difference that was significant based on the ALK (5A4) scores." (PMID 28837676, 2017). "Since the amount of frozen tumor tissue was insufficient to perform protein analysis, we grouped NB tumor samples on the basis of their different ALK mRNA expression levels, thus identifying an ALK+ and an ALK- subgroup, each consisting of 11 samples." (PMID 28915608, 2017). "We intended to explore the heterogeneity of ALK gene translocation in excision specimens and to examine the existence of discordance of ALK status between primary tumours and corresponding lymph node metastases." (PMID 28887531, 2017). "As an oncogenic driver, aberrant ALK has been recognized as the central trigger of the development of a number of different tumor types, including hematopoietic, epithelial, mesenchymal and neural neoplasms." (PMID 28535796, 2017). "Tumor tissue genotyping is used routinely in cases of lung cancers to identify specific and targetable oncogenic alterations, including EGFR mutations and ALK rearrangements." (PMID 28392479, 2017). "Tumor recurrences occurred in a total of 199 patients (37.3%), 25 of whom (12.6%) were in the ALK IHC-positive group and 174 (87.4%) in the ALK IHC-negative group." (PMID 29156778, 2017). "ALK was the most significantly overexpressed gene in tumor tissue of MCC patients, with a log2fold change of 7.6." (PMID 28359267, 2017). "We next retrospectively analyzed the 37 selected tumor samples for which the ALK fusion status had been previously determined using conventional techniques (IHC and FISH)." (PMID 28970558, 2017). "We assessed MYCN and ALK copy numbers from archived single tumor biopsies from the 10-patient pilot cohort in this study as the control measure for copy number detection using the paired plasma samples." (PMID 29156716, 2017). "This pathology-defined prognosis is also dependent on both tumor stage and the status of genetic mutations in the EGFR, KRAS, ALK, RET, and BRAF genes." (PMID 29137260, 2017). "As a multi-faceted approach to eradicate tumor cells, combined therapies for ALK-positive ALCL are currently being studied." (PMID 29186933, 2017). "The concordance rate of ALK rearrangement between primary tumor and paired metastatic lymph nodes was detected by immunohistochemistry (IHC) and FISH." (PMID 29312572, 2017). "We investigated the immune profiles of IMTs, including PD-L1 expression and proportion of CD8+ tumor-infiltrating lymphocytes (TILs), as well as its clinicopathological characteristics according to ALK gene rearrangementstatus." (PMID 29163763, 2017). "Similarly to EGFR-mutant tumours progressing under TKIs, patients harbouring ALK rearrangements will ultimately acquire resistance to crizotinib due to a variety of mechanisms, with secondary ALK mutations representing the most investigated, and with CNS as one common site of metastatisation." (PMID 29225694, 2017). "Using the AMP target enrichment technique on the same 37 tumor samples, we detected the presence of ALK fusion transcripts in 15 specimens." (PMID 28970558, 2017).